TNF (tumor necrosis factor)
Diseases named in the same sentence as TNF in open-access papers (continued):
Sharing a sentence is not in itself a finding about the gene and the disease.
tumor (continued). "Additionally, pro-inflammatory cytokines such as TNF-α and IL-6 can exacerbate tumor progression by promoting chronic inflammation, further hindering the efficacy of immunotherapies." (PMID 40109332, 2025). "TNF-α is a cytokine with tumor necrosis activity and plays a role in inflammation." (PMID 41334449, 2025). "However, TNF-α can also promote tumor growth, migration, and invasion, potentially through activation of the Wnt pathway and establishment of a tumor-permissive niche." (PMID 40909271, 2025). "For example, CD4 + T cell-derived EVs enriched with pro-inflammatory cytokines such as IFNγ, TNFα and IL-2, are taken up by macrophages to sustain M1 anti-tumor phenotype and to stimulate cGAS-independent STING activation, subsequently inhibiting CRC progression." (PMID 40908470, 2025). "These cells might also promote inflammatory responses by secreting cytokines, such as IFN-γ and TNF-α, which could further contribute to tumor growth." (PMID 41301424, 2025). "Mgl2 KO tumors displayed significant enrichment of immune and inflammatory pathways, including TNF-α/NF-κB, IL-6/JAK-STAT3, interferon-α/γ, and IL-17 signaling—pathways broadly associated with myeloid activation, cytokine production, and tumor immunosurveillance 53,54." (PMID 41377951, 2025). "Although TNF-α can play a dual role in cancer biology, capable of exerting both tumor-suppressive and tumor-promoting effects (see Section 3), in TNBC, TNF-α is primarily associated with tumor progression, invasiveness, and angiogenesis." (PMID 40868199, 2025). "Moreover, tumor cell stemness characteristics and inflammatory cytokines (e.g., TNFα, IL-6) promote upregulation of adhesion molecules on tumor cells, facilitating the formation of CTC clusters in peripheral blood." (PMID 40547026, 2025). "Additionally, pectin, particularly MCP, has been shown to decrease the levels of proinflammatory cytokines such as IL-6, TNF-α and IL-1β, which are often elevated in the tumor microenvironment and contribute to tumor progression." (PMID 41249064, 2025). "In cancer, TNF signaling may exhibit dual functions, either facilitating the death of tumor cells or supporting their survival, which is contingent upon the cellular environment and the interplay of subsequent signaling events." (PMID 41011149, 2025). "Furthermore, TNF-α signaling was significantly enriched in late progressors, underscoring its role in driving chronic inflammation, reshaping the tumor immune microenvironment, and enhancing tumor survival under therapeutic pressure." (PMID 39955556, 2025). "These AGEs activate inflammatory signaling cascades such as the NF-κB and STAT3 pathways, resulting in increased production of pro-inflammatory cytokines (e.g., interleukin-6 and tumor necrosis factor-alpha) that induce DNA damage, inhibit apoptosis, and promote tumor progression." (PMID 41479778, 2025). "Moreover, tumor-associated signaling pathways, including NF-κB, Toll-like receptor, JAK-STAT, and TNF signaling, were significantly enriched in the 3D model." (PMID 40416783, 2025). "Furthermore, percentages of TNF-α+CD8+ Tand GZMB+CD8+ T cells in tumor tissues were notably increased by sh-TBX21, indicating a shift toward a more active antitumor immune microenvironment." (PMID 41573646, 2025). "The TME in CRC is often characterized by chronic inflammation, where inflammatory mediators such as cytokines (e.g., TNF-α, IL-6), chemokines, and immune cells (e.g., macrophages) contribute to tumor progression and metastasis through activation of key signaling pathways, including PI3K/AKT." (PMID 41179295, 2025). "Notably, a higher proportion of dual ABE-TILs than Mock-EP TILs produced IFN-γ and TNF-α upon co-culture with autologous target tumor cells." (PMID 41394272, 2025). "Notably, this study also observed a decrease in resting mast cells, which can actively eliminate tumor cells and prevent tumorigenesis through cytokines, such as IL-1, IL-4, IL-6, and TNF-α." (PMID 40755754, 2025).
tumor (continued). "Furthermore, as other immune cell types such as T cells can also produce TNF-α, the contribution and crosstalk of these immune cells in regulating tumor pyrimidine metabolism remain to be further investigated." (PMID 41243973, 2025). "Importantly, in addition to its antitumor role, the immune system can stimulate tumor growth through signaling with certain cytokines (IL-1β, IL-23, IL-11, IL-6, TNF, and GM-CSF)." (PMID 40697381, 2025). "However, no intergroup differences were observed in IL34 levels in the blood, indicating that IL34 secretion by BI PitNETs is confined to the tumor microenvironment, where the excessively secreted IL-34 can act on TNF-α+ TAMs." (PMID 39865310, 2025). "Tumor immunogenicity depends on tumor-associated antigens (TAA) presented on MHC class I molecules, recognized by CD8+ cells that trigger apoptosis, cell cycle arrest, and the release of anti-tumor mediators like IFN-γ and TNF-α." (PMID 40867260, 2025). "Furthermore, we also analyzed the expression of TNF‐α, IL‐6, and IL‐10 genes in tumor tissues, which were consistent with the ELISA results, with the most significant changes observed in the CB‐AKK combined group improved by 19 times." (PMID 40497373, 2025). "Additionally, in experimental models, blocking TNF or TNFR2 in vivo reduces tumor growth while limiting effector Tregs." (PMID 40977146, 2025). "In contrast, untreated mice showed a higher mean tumor area with low levels of TNF-α and IFN-γ." (PMID 41011849, 2025). "This activation leads to the release of IL-6, TNF-α, and other inflammatory cytokines that enhance neutrophil effector functions, including phagocytosis and ROS production, which contribute to the elimination of tumor cells." (PMID 40486614, 2025). "KEGG pathway enrichment analysis demonstrated that differentially expressed genes in CAR-M were predominantly enriched in inflammation-associated pathways, including Toll-like receptor, TNF, RIG-I-like receptor, and NF-κB, indicating robust tumor-triggered inflammatory activation." (PMID 41388305, 2025). "On the other hand, TGF-β, TNF, IL-1β promote tumor cell proliferation." (PMID 41333471, 2025). "Furthermore, ELISA analysis revealed a significant increase in IFN‐γ, TNF‐α, and IL‐2 cytokine levels in the tumor tissue following the administration of C‐N‐LNPs‐vaxD18 compared to Mix‐vax or PBS treatment." (PMID 40125791, 2025). "Tumor-derived TNF-α activates the NF-κB pathway to induce PD-L1 expression on mast cells." (PMID 40091086, 2025). "These molecules were demonstrated to modulate the production of pro-inflammatory cytokines, decreasing TNF-α and IL-1β release and increasing anti-inflammatory cytokine interleukin-10 (IL-10) by mouse peritoneal cells, lyse human tumor-derived cells, and mouse erythrocytes." (PMID 41003528, 2025). "KYNA may exert anti-inflammatory effects through inhibition of tumor TNF-α induced by lipopolysaccharides in peripheral blood mononuclear cells." (PMID 41009721, 2025). "Consistently, although functional analysis demonstrated the enrichment of anti-tumor pathways, including T-cell activation, and TNF- and NF-κB signaling pathways in T cells from SC models, they also exhibited significant enrichment in pro-tumor IL-17 signaling pathways." (PMID 40899264, 2025). "Furthermore, in the context of chemotherapy-induced tumor immunogenicity, Panx1 facilitates ATP release through a caspase-3-dependent mechanism activated by TNF-α." (PMID 40978734, 2025). "In vitro TNF stimulates the proliferation of fibroblasts, astrocytes, macrophages, T-lymphocytes, and B-lymphocytes, but has a cytotoxic effect on various tumor cell lines and normal cells, such as endothelial, oligodendrocytes, thyrocytes, and fibroblasts." (PMID 40427602, 2025).
tumor (continued). "Previous studies have revealed that tumor cells can produce and release some inflammatory mediators, such as tumor necrosis factor-alpha and interleukin-6, which may inhibit the synthesis of albumin in the liver, potentially resulting in hypoproteinemia." (PMID 40265018, 2025). "The main manifestations of the biological activity of TNF-α are as follows: selective cytotoxicity against some tumor cells, inhibition of the synthesis of the key enzyme of lipogenesis-lipoprotein kinase, participation in the regulation of the immune response and inflammation." (PMID 40806737, 2025). "Additionally, TNFα can stimulate the production of growth factors that support tumor cell survival and proliferation." (PMID 40743051, 2025). "Other factors, including IL17A, IL1, and TNF(denoted by black arrows), were also activated, whose functions might initiate tumor progression." (PMID 40225855, 2025). "Correspondingly, intratumoral levels of IFN-γ, TNF-α, and Gzm-B were significantly elevated, resulting in robust cytotoxicity against tumor cells and substantial inhibition of tumor growth." (PMID 41406950, 2025). "This process is mediated by the activation of signaling pathways such as activator protein 1 (AP-1), Wnt/β-catenin, and the upregulation of cyclin D1, which collectively induce a pro-tumor inflammatory microenvironment infiltrated by TNF-α and Tregs, thereby promoting mammary tumorigenesis." (PMID 41597595, 2025). "Gene set enrichment analysis (GSEA) further showed hallmarks of anti-tumor immune responses being upregulated in the mDKN01-treated tumors compared to IgG, including interferon-gamma response, interferon-alpha response, TNFα signaling via NFκB, and IL-2/STAT5 signaling." (PMID 39885132, 2025). "Neutrophils and key signaling pathways, such as NF-κB and cytokines like TNF-α and IL-6, enhance tumor progression, which may explain the observed increase in NLR in more aggressive tumors." (PMID 40141182, 2025). "The increased tumor suppression by Usp22 deletion is associated with increased tumor cell surface H-2Kb and β2M expression, the elevated tumoral-infiltrating CD8+ T cells and their production granzyme B, IFN-γ, and TNF-α." (PMID 41252204, 2025). "TNF blockade promotes mucosal healing in patients with inflammatory bowel conditions, potentially mitigating abnormal cell growth and subsequent tumor formation in the colon while modifying microbiota composition and activities, thus attenuating colorectal carcinogenesis." (PMID 39980561, 2025). "Furthermore, MSCs' high proliferative capacity and tumor-homing potential enable recruitment into tumor microenvironments in response to hypoxia or pro-inflammatory cytokines (e.g., IL-1β, TNF-α, IFN-γ)." (PMID 41169880, 2025). "Additionally, TNF-R2—shown in our study to correlate with VS tumor size—plays an important role in TNF-dependent immunosuppression." (PMID 39923035, 2025). "Finally, we showed that Ykiact induce cell death in non-tumor cells through the regulation of Egr/TNF alpha and /JNK signaling." (PMID 39829769, 2025). "However, pGSN interferes with this process by inducing apoptosis in M1 macrophages and reducing their production of NO and TNFα, thereby inhibiting their anti-tumor function." (PMID 40330466, 2025). "Furthermore, UA modulates the inflammatory tumor microenvironment by downregulating the expression of proinflammatory cytokines, such as IL-6 and TNF-α, which play crucial roles in tumor growth and metastasis." (PMID 40568370, 2025). "TNF-α expression was significantly upregulated, indicating that cell death signals may have been transduced into the tumor immune microenvironment to produce a synergistic antitumor response." (PMID 41008944, 2025). "Furthermore, Mg2+ has been shown to inhibit tumor invasion and metastasis by downregulating the TNF-α/IL-1/NF-κB signaling cascade." (PMID 41367628, 2025). "Within this tumor microenvironment, cancer cells may develop resistance to the inhibitory effects of TNF-α." (PMID 41450917, 2025).
tumor (continued). "Variability in the immune cell composition of the tumor microenvironment between patients may have contributed to the observed differences in TNF-α secretion levels." (PMID 39923035, 2025). "Furthermore, the abnormal secretion of inflammatory factors (such as IL-6 and TNF-α) from adipose tissue in women with GDM can create a tumor-promoting microenvironment." (PMID 40678319, 2025). "Our results suggest that IL-2 and TNF-α should be evaluated in a larger study to better understand their role in pathogenesis and prognosis, as they showed a significant relationship or a trend of relationship with tumor stage and PR." (PMID 40869161, 2025). "First, this process may be due to inhibition of TNFα-mediated cytotoxicity against tumor cells or suppression of immune effector cell function." (PMID 40282506, 2025). "Chronic inflammation and oxidative stress induced by prolonged hypertension contribute to vascular endothelial dysfunction, increased ROS, and elevated pro‐inflammatory cytokines such as IL‐6, TNF‐α, and NF‐κB, which can lead to DNA damage and tumor progression." (PMID 40387523, 2025). "Additionally, qPCR analysis demonstrated increased expression of interferon-γ and tumour necrosis factor-alpha (TNFα) in the tumours of the CD44-IR700_IT group when compared to the CD44-IR700_IV group." (PMID 39848206, 2025). "In addition, BET inhibitors (RG6146 and JQ1) sensitize tumor cells to TNF-mediated cytotoxicity by blocking BRD4-dependent NF-κB survival programs in tumor cells." (PMID 41583469, 2025). "Functional analysis of the induced T-cell response in the blood of LS-CoAT-vaccinated animals revealed comparable frequencies of IFNγ/TNFα double-positive Adpgkmut-specific CD8 T cells after complete tumor regression, indicating fully functional cytotoxic effector T cells." (PMID 39741195, 2025). "On the one hand, TNF-α plays a key role in enhancing the antigen-presenting function and promoting the release of inflammatory factors, thereby providing the body with an effective anti-tumor immune environment." (PMID 41376630, 2025). "This analysis suggested that p38 could activate the downstream tumor-promoting inflammatory factors, such as TNF, IL1B, and NFkB, which are predicted to be the top-activated factors in the GBM PNZ." (PMID 39805854, 2025). "NK cells mediate the tumor killing also triggering apoptotic pathways in tumor cells through the production of TNF-alpha or via direct cell–cell contact through activation of the Tumor necrosis factor (TNF)-related apoptosis-inducing ligand (TRAIL) and FAS ligand (FASL) pathways." (PMID 39981232, 2025). "Tumor-infiltrating macrophages secrete TNFα, which in turn promotes tumor growth." (PMID 41300698, 2025). "Specifically, the mice exposed to both FMT acceptability for donation and immunotherapy with anti-PD1 demonstrated a 2.5-fold increase in IFN-γ levels and a 1.8-fold increase in TNF-α within the tumor microenvironment when compared to controls, reflecting a higher systemic anti-tumor immunity." (PMID 40002939, 2025). "These accumulated cells include M1-polarized macrophages and differentiated moDCs, which may secrete TNF-α and reactive oxygen species to directly kill tumor cells." (PMID 40977690, 2025). "Moreover, zinc supplementation has been shown to reduce the vulnerability of tumor cells to TNF-dependent lysis mediated by CD8+ T cells, whereas zinc chelation enhances this susceptibility." (PMID 40390089, 2025). "The mechanisms by which anti-TNFα agents may contribute to carcinogenesis are multifaceted and include changes in immune function, modulation of the tumor microenvironment, and effects on cell signaling pathways." (PMID 40282506, 2025). "Three immune signaling pathways, including JAK-STAT, NF-κB, and TNF signaling pathways, are conspicuously augmented in the primary tumor sites of HRD cancers, which might imply the origin of the immune signal of HRD tumor cells." (PMID 40830526, 2025).
tumor (continued). "In addition to TNF-α (Padj < 0.001), tumor tissue from the TNF-α High group secreted significantly higher levels of MIF and IL-10 (both Padj < 0.05)." (PMID 39923035, 2025). "Moreover, pre-treatment of Tregs with TNF-α prior to adoptive transfer enhances their suppressive capacity against anti-tumor immunity." (PMID 41200178, 2025). "Additionally, HBOT modulates inflammation factors (such as IL-10 and TNF-α) and antioxidant pathways (such as Nrf2), improving the metabolic activity of immune cells and enhancing their anti-tumor functions." (PMID 40552269, 2025). "Conversely, TNF blockade with a sTNFR2‐Fc improved tumor therapy in mouse models." (PMID 40977146, 2025). "TNF-R2 may also collaborate with TNF-α and other proinflammatory cytokines, such as IL-6, to enhance VS tumor growth, as its expression can be jointly driven by TNF-α and IL-6." (PMID 39923035, 2025). "Moreover, TNF-α was discovered to be a useful cancer treatment tactic since it dramatically reduced tumor growth and stopped tumor spread." (PMID 39570546, 2025). "The TNF-α/NF-κB pathway accelerates the tumor cell cycle and growth." (PMID 41458591, 2025). "In addition to NK cell-mediated tumor cell killing, we analyzed the capacity of these DuoBody variants to trigger immunomodulatory interferon-γ (IFN-γ) and tumor necrosis factor α (TNF-α) cytokine release." (PMID 39811682, 2025). "To further validate our transcriptomic findings, we assessed the protein expression levels of TNF-α and IL-1β—two cytokines that showed statistically significant differences in gene expression—using Western blot and immunohistochemistry (IHC) in tumor tissue samples." (PMID 40565357, 2025). "Additionally, we evaluated the ability of CD155 CAR-T cells to produce key cytokines involved in tumor eradication, such as TNF and IFN-γ." (PMID 40478751, 2025). "For instance, while inhibiting IL-6 or TNF-α may reduce inflammation and tumor growth, it could also compromise the body’s ability to fight infections or control tumor progression." (PMID 40563999, 2025). "In SIRT6 TG mice, decreased TNFR2 inhibited tumour‐secreted‐TNFα induced adipose lipolysis." (PMID 39971710, 2025). "Significantly, TNF-α may induce drug resistance in tumor cells by activating the Hedgehog (Hh) signaling pathway." (PMID 41450917, 2025). "IL-6 and TNFα, key mediators in inflammatory processes, are central targets in immunotherapy due to their roles in tumor progression and immune modulation and their activity influencing nearly all biological processes, depending on the production levels and surrounding conditions." (PMID 40004468, 2025). "Furthermore, a separate study has suggested that the inhibition of TNF-α expression can lead to an upregulation of IL-33 in tumor cells, which in turn enhances the activity of DCs and cytotoxic T cells, thereby promoting anti-tumor immunity." (PMID 40948749, 2025). "For example, indole can promote the polarization of TAMs toward the M1 type through the mTOR signaling pathway, secrete pro-inflammatory cytokines such as TNF-α and IL-12, promote the Th1 type of immune response, and enhance the killing ability against tumor cells." (PMID 40183013, 2025). "Tumor cells damage endothelial cells, increasing adhesion molecule expression and releasing inflammatory cytokines such as interleukin-6 (IL-6) and tumor necrosis factor-alpha (TNF-α), which amplify coagulation and inhibit fibrinolysis." (PMID 39857994, 2025). "In terms of phenotypic polarization, the formation of N1-type TANs may be associated with the exposure of cytokines such as interferon (IFN) and TNF-α, which promote anti-tumor immune response." (PMID 40160822, 2025). "Furthermore, 4-1BB signaling also stimulated CD4+ effector T cells to expand and produce proinflammatory cytokines, such as IFN-γ and TNF-α, providing a proinflammatory environment that favored tumor rejection." (PMID 40067370, 2025).